NES (nestin)
Diseases named in the same sentence as NES in open-access papers (continued):
Sharing a sentence is not in itself a finding about the gene and the disease.
glioblastoma (continued). "Knockdown of nestin in glioblastoma reduced sphere formation and the expression of stemness genes proving that it may be a useful target." (PMID 33171868, 2020). "Additionally, miR-423-5p through suppression of its target gene (ING-4) increased Nestin expression in GSCs and accordingly induced glioblastoma cells to exhibit greater resistance to TMZ." (PMID 32429463, 2020). "Additionally, anti-nestin antibodies were attached to the system in order to target nanoparticles to the glioblastoma." (PMID 30791358, 2019). "For example, Nestin has been observed in the nucleus of glioblastoma and neuroblastoma cells." (PMID 30190500, 2018). "Furthermore, the coexpression of ObR and CD133, as well as Nestin, indicated the ObR-positive glioblastoma cells were GSCs." (PMID 28938545, 2017). "We show that KLF6 overexpression often reduced NESTIN and increased neural genes expression in glioblastoma cells and LN229-KLF6-wt derived tumors, suggesting that KLF6-wt could reduce stemness and induce neural differentiation." (PMID 28166199, 2017). "Cells could be propagated for multiple passages (10 passages tested in our laboratory) without significant differentiation as shown by the expression of glioblastoma TICs marker, Nestin, in the majority of cells." (PMID 27549983, 2016). "Mer receptor expression is maintained in primary glioblastoma-derived tumor spheres and correlated with the expression of Nestin and Sox2 in a glioblastoma spheroid culture model, suggesting that Mer is crucial for the maintaining an undifferentiated state of cells." (PMID 27028863, 2016). "Immunohistochemistry on the glioblastoma sample revealed a diffuse nestin staining pattern." (PMID 26018884, 2015). "Therefore, hepatocellular carcinoma is a more suitable option for a nestin-positive control than glioblastoma, when using fluorescent immunohistochemistry." (PMID 26018884, 2015). "Furthermore, a recent study has demonstrated a substantial survival advantage of genetic targeting of glioblastoma cancer stem cells using a neural stem cell marker Nestin." (PMID 25010414, 2014). "Our phosphoproteome data also indicated that some marker molecules for glioblastoma initiating cells, such as nestin and vimentin, were found to be highly phosphorylated with many novel phosphorylation sites in addition to previously reported ones on these key molecules." (PMID 22912867, 2012). "In addition, Nestin has been also identified in the cell nucleus of tumor cell lines obtained from glioblastoma patients." (PMID 19108713, 2008). "Detailed information concerning the pattern of the nestin cytoskeleton in glioblastoma cell lines and especially the demonstration of nestin in the nucleus represent an important background for further studies of nestin re-expression in relationship to tumor malignancy and invasive potential." (PMID 16457706, 2006). "Moreover, hallmarks of atypical pTrk kinase were found in biopsies of Nestin-positive glioblastoma." (PMID 39039193, 2024). "Indeed, tumor cells which express markers associated with the stem cell functional phenotype, such as Notch, Wnt, ABCB5, CD133, CD166, nestin, and c-kit, and significantly contribute to the establishment of tumor vasculature have been observed in aggressive melanoma and glioblastoma." (PMID 34299320, 2021). "GSI RO4929097, in combination with radiation and TMZ, decreases the expression of CD133, SOX2, and nestin (inducing neural and astrocytic differentiation), has an anti-proliferative effect (reducing 3D spheroid growth), and increases the survival of the orthotopic Glioblastoma mouse model." (PMID 30832246, 2019). "Finally, we examined the protein levels of the stem cell markers sox2 and nestin in the primary glioblastoma cell line T269 after DHA treatment to assess whether DHA can induce differentiation." (PMID 27447560, 2016).
glioblastoma (continued). "Therefore, as a first step to establish if TDZD-8 could affect the CSC population in GL261 glioblastoma cells, we examined its effect on the expression of Nestin in adherent cultures of GL261 cells." (PMID 21079728, 2010). "For example, due to the hybrid nestin enhancer-HSP68 minimal promoter, expression of the virulence gene γ34.5 was restricted to nestin-positive glioblastoma cells." (PMID 40697381, 2025). "In glioblastoma, cooperation between the Notch and RAS pathways leads to the development of CSCs-like populations that express higher levels of nestin, a glioblastoma stem cell marker." (PMID 40003637, 2025). "Lastly, further characterization of the enriched stem cell-like state compartment in glioblastomas with a mesenchymal transition revealed an increased abundance of stem cell markers SOX2, PROM-1, and Nestin." (PMID 38244080, 2024). "TRIM8 re-localizes from the cytoplasm of healthy neurons to the nucleus in GBM cells to establish a stem-like phenotype, with an increase in malignancy and glioblastoma stem cell markers, such as STAT3, SOX2, Nestin, and Nanog." (PMID 38115822, 2023). "In rQNestin34.5, UL34.5 has been reintroduced into the HSV-1 genome under the control of the glioblastoma multiforme (GBM) specific promoter, nestin." (PMID 35965554, 2022). "The established PD-GBOs shared known morphological features of glioblastoma including the presence of GFAP and nestin-labeled tumor microtubes (TMs), extensions that connect individual glioblastoma tumor cells to each other." (PMID 35743016, 2022). "Two other IF proteins were also analyzed in these glioblastoma cell lines: glial fibrillary acidic protein (GFAP) and nestin." (PMID 35701472, 2022). "The level of LASS2 is significantly lower in GSCs than in non GSCs, whereas LASS2 overexpression reduced the sphere formation and promoted the differentiation of CD133+ glioblastoma cells, as was indicated by reduced levels of CD133 and Nestin." (PMID 35517425, 2022). "The verified protein expression of the progenitor markers NES and SOX2 in the adherent primary glioblastoma cell lines established here is indicating that the cells retained at least the ability to dedifferentiate, if not potential stem cell properties." (PMID 33251771, 2021). "Recently, the putative markers frequently being used to identify and/or isolate glioblastoma stem cells (GSCs) include: CD133, CD44, CD15, CD70 (CD27 L), S100A4, ALDH1A3, Nanog, OCT-4, SOX-2, and Nestin." (PMID 32429463, 2020). "miR-381 suppression has been sensitized by glioblastoma cells to TMZ by preventing stemness factors, including Nestin." (PMID 32429463, 2020). "Lck mediates the expansion of the CD133+ GSC pool following ionizing radiation of glioblastomas and inhibition of Lck inhibits the radiation-induced expression of CD133, Nestin, and Musashi in GSCs." (PMID 30353164, 2019). "In glioblastoma, anti-miR-182 expression results in increased expression of biomarkers for proliferation and stem cell biomarkers (e.g., CCNB1, CD44, Sox2, and Nestin)." (PMID 31007608, 2019). "The oncogenic role of Notch1 can also be due to the infection of human cytomegalovirus, which upregulates Notch1, ATF5 (an anti-apoptotic protein already highly expressed in Glioblastoma), and stem cell markers CD133, nestin, SOX2, OCT4, KLF4, and BMI-1." (PMID 30832246, 2019). "Reduced expression of nestin by shRNA in NSCLC cell line H1975, pancreatic cancer cell line PANC, and glioblastoma cell line A172 showed decreased sphere formation in vitro, which measures the self-renewal capacity of cancer cells." (PMID 31126068, 2019). "We found AMG232 suppresses Nestin and ZEB1 indicating the inhibitor leads to inhibition of the glioblastoma stemness." (PMID 30022047, 2018). "Double-immunofluorescence stainings in glioblastomas revealed co-expression of JAM-A with CD133, SOX2, nestin, and GFAP in tumor cells as well as some co-expression with the microglial/macrophage marker IBA-1." (PMID 28677106, 2017).
glioblastoma (continued). "In glioblastoma tissues, we confirmed that VM numbers was correlated with GSC markers expression, such as CD133, Nestin." (PMID 28938545, 2017). "Our research indicated that either suppressing miR-381 or enhancing NEFL expression sensitizes glioblastoma cells to TMZ by inhibiting stemness factors (ALDH1, CD44, CKIT, KLF4, Nanog, Nestin, and SOX2)." (PMID 25605243, 2015). "Glioblastoma subpheres analysis revealed that most CD133 isolated cells co-expressed GFAP and Nestin, relating the isolated cells with neural and stem cell origin." (PMID 24432012, 2014). "Glioblastoma cells forming aggregates, as well as undifferentiated GFAP+NNP, co-expressed SOX-2, Nestin, Beta III-tubulin, MAP2, GFAP, Vimentin, Fibronectin and CD44, when cultured under serum-starvation media." (PMID 19216795, 2009). "One discrepancy between glioblastoma cells and GFAP+NNP was sustained Nestin expression in neural derivatives of glioblastoma cells." (PMID 19216795, 2009). "There was a surprisingly high level of expression of stem cell markers in the paediatric glioblastoma lines, with both SF188 and KNS42 strongly positive for nestin, and containing 7% and 4% CD133-positive cells respectively." (PMID 19365568, 2009). "Coexpression of nestin and CD133 (also known as prominin-1) is considered to be a marker for cancer stem cells (CSCs); this fact was experimentally proven in glioblastoma multiforme and malignant melanoma." (PMID 18925963, 2008). "Also, we have previously demonstrated the colocalization of mHsp70 with markers of tumor stem-like cells (Nestin, SOX2) in glioblastoma cells." (PMID 41094345, 2025). "Supporting evidence from glioblastoma stem cells shows that POSTN enhances self-renewal and malignancy via activation of the αvβ3/PI3K/AKT/β-catenin/FOSL1 pathway, upregulating key stemness markers such as CD133, Nestin, and SOX239." (PMID 40520021, 2025). "Moreover, HH is involved in regulating tumor spheroid formations, as observed in the case of glioblastoma (GBM) neurospheres, by controlling NANOG.; nestin, BMI1, and gene expression." (PMID 35205721, 2022). "A growing body of evidence supports the presence of a population of cells in glioblastoma (GBM) with a stem cell-like phenotype which shares certain biological markers with adult neural stem cells, including expression of SOX2, CD133 (PROM1), and NES (nestin)." (PMID 36333778, 2022). "The expression of Nestin, Musashi and OPN was significantly increased in recurrent glioblastoma." (PMID 35183162, 2022). "Beside glioblastoma cell lines, we also showed that endogenous Survivin is predominantly localized to the nucleus of HGG patients’ tissue, irrespective of putative NES mutations, which are very rare and did not correlate with patients’ survival." (PMID 34100981, 2021). "As such, inhibition of Nestin and/or HSC71 may be a beneficial molecular target therapy for glioblastoma." (PMID 32429463, 2020). "Unfortunately, discrimination between fibroblasts and cells from the glioblastoma cell line T98G was not possible using the nestin-specific antibody." (PMID 30123089, 2018). "Taken together, we identified a set of miRNAs that are differentially expressed in GSCs as compared to non-stem glioblastoma cells, several of which correlated with the expression of the stem cell markers Sox-2 and nestin." (PMID 29434344, 2018). "Furthermore, glioblastomas share several membrane markers expressed by NSCs, including CD133, Nestin, SOX2, and GFAP." (PMID 30279357, 2018). "Similar to glioblastoma stem-like cells, NSCs failed to express the stemness marker Nestin when treated with 10 μM of FAD." (PMID 30388862, 2018). "Similar markers of human glioblastoma cells were also expressed as confirmed by comparable expression of specific proteins of human glioblastoma such as vimentin and nestin (data not shown)." (PMID 29156770, 2017).
glioblastoma (continued). "CD9 silencing in three CD133+ glioblastoma cell lines (NCH644, NCH421k and NCH660h) led to decreased cell proliferation, survival, invasion, and self-renewal ability, and altered expression of the stem-cell markers CD133, nestin and SOX2." (PMID 26573230, 2016). "Two CD150 negative glioblastoma cases were characterized by high levels of nestin and GFAP expression." (PMID 25710480, 2015). "Namely, a restricted cell population of Ki-67 negative and nestin positive cells was identified in a murine glioblastoma model and stem-like cells with molecular signatures applying to slow-rate dividing cells were evidenced by a single-cell RNA-seq approach." (PMID 26270679, 2015). "To further characterize gene expression in the Ad-GSCs and Sp-GSCs tumor xenografts, we examined the expression of genes previously defined to be characteristic of the Classical (FGFR3, PDFA, EGFR, AKT-2 and Nestin) and Mesenchymal (CHI3L1, TRADD, NF1, RelB and CASP4) glioblastoma subtypes." (PMID 25955030, 2015). "Biopsy samples from glioblastoma patients showed that integrin-α6-positive cells are localized in close proximity to the tumor vasculature and often coexpressed the stem cell markers CD133 and nestin." (PMID 22685459, 2012). "The high-grade astrocytomas, i.e. anaplastic astrocytoma (WHO grade III) and glioblastoma multiforme (WHO grade IV), seem to be exceptionally suitable models for the investigation of nestin re-expression and its relationship to the other intermediate filament proteins." (PMID 16457706, 2006). "In glioblastoma, these cells are referred to as GBM stem cells (GSCs) and exhibit characteristics similar to normal neural stem cells (NSCs), such as the expression of stem cell markers (e.g., CD133, Nestin) and the capacity to differentiate into multiple neural lineages." (PMID 40277888, 2025). "Although PARD3 expression is differentially regulated in human cancers, and PARD3 may function as either an oncogene or tumour suppressor depending on cancer subtype or stage, a recent study showed that in human glioblastoma, PARD3 was enriched in NESTIN-positive stem cells." (PMID 38317186, 2024). "Both Nestin, an intermediate filament protein, and CD133, a stem cell marker frequently used to isolate cancer stem cells, are expressed by normal neural stem and progenitor cells and have been previously used to identify and isolate glioblastoma stem-like cells." (PMID 36823554, 2023). "Using nestin as a CSC biomarker, they found that nestin-expressing CSCs in glioblastoma (GBM), medulloblastoma, ependymoma, and oligodendroglioma were significantly closer to tumor blood vessels than tumor cells not expressing nestin." (PMID 36091174, 2022). "In other recombinant oHSVs, to complement γ134.5 deletion and maintain glioblastoma specificity, heterologous genes as the human GADD34 gene (for oHSV NG34) or the IRS1 gene from cytomegalovirus (for oHSV C134) were engineered into the viral genome under the control of the nestin promoter." (PMID 34578259, 2021). "Thus, rQNestin replication is impaired in cells that do not express Nestin, and robust replication is only seen in Nestin-expressing glioblastoma cells." (PMID 33535555, 2021). "Indeed, exposure of glioblastoma stem-like cells to recombinant BMP7 in vitro increased SMAD1/5/8 phosphorylation, inhibited cell proliferation, stimulated glioblastoma differentiation, decreased neurosphere formation and attenuated expression of the stem-like genes Nanog, SOX2, Nestin and Olig2." (PMID 29799477, 2018). "Likewise, low expression of BRY has been found at mRNA levels in rhabdomyosarcomas, and NESTIN in neuroblastomas and glioblastomas but not at the protein level (and data not shown)." (PMID 21785609, 2011). "Nestin is overexpressed in glioblastoma (GBM) and other aggressive tumors but is not expressed in adult brains or healthy differentiated tissues." (PMID 40352942, 2025).
glioblastoma (continued). "Its effect on a subpopulation of GBM cells exhibiting glioblastoma stem cell (GSCs)-like characteristics revealed a reduced expression of Oct4, Sox2, CD133, CD44, and a decrease in ALDH+, Nestin+ and CD44+ cells." (PMID 36231019, 2022). "In line with the hypoxia-induced upregulation of CD133 and nestin found in the present study, SOX-2 has previously been reported to be upregulated in response to hypoxia and SOX-2 might therefore play an important role in hypoxia-induced biology of glioblastoma." (PMID 29708435, 2018). "The observed IQGAP1+/Iba1+/nestin+ cells could represent a common ancestor for TAMs and GBM tumorigenic neural precursors and/or, probably, an interconvertible multipotent progenitor cell form of both kinds and/or glioblastoma amplifying cancer cells (GSCs or progenitor cells)." (PMID 28098764, 2017). "However, APLN staining did not coincide with NESTIN-positive tumour cells, but rather with vascular tracks, supporting endothelial cells as a potential source for apelin in glioblastoma, consistent with a recent report in colorectal cancer-derived endothelial cells." (PMID 29053791, 2017). "Alterations of post-translational expression of HSP70 by the stemness marker nestin has been shown to regulate tumor growth and invasiveness in glioblastoma via cyclin D1 and therefore an inhibition of both HSP70 and nestin might improve outcome of glioblastoma patients." (PMID 26771644, 2016). "Moreover, nestin-positive endothelial cells and nestin-negative endothelial cells may be found in the same rat brain: for example, in glioblastoma and in normal adjacent tissue, respectively." (PMID 26018884, 2015). "Different expression levels of Olig2, Nogo-A, Nestin and AQP4 have no independent prognostic impact in IDH-wildtype glioblastoma and show no distribution differences regarding age, clinical status and MGMT-promoter methylation status." (PMID 32160197, 2020). "In our culture model, a population of glioblastoma cells was able to form aggregates composed of cells with multilineage phenotype, i.e. showing expression of: CD44, Vimentin, GFAP, Nestin, Beta III-tubulin, MAP2, Fibronectin and SOX-2, but not CD133." (PMID 19216795, 2009). "Although not a definitive neural stem cell marker, nestin is expressed in the minor-population of tumor stem cells derived from brain tumors that have recently been shown to contribute towards tumorigenicity and therapeutic resistance in glioblastoma (GBM)." (PMID 18817556, 2008).